THBS1 (thrombospondin 1)
Diseases named in the same sentence as THBS1 in open-access papers (continued):
Sharing a sentence is not in itself a finding about the gene and the disease.
tumor (continued). "Using Snail1 overexpression models of melanoma cells, it was suggested that TGF-β and thrombospondin-1 (TSP1) production apparently generated immunosuppressive Treg cells and non-responsive CD8+ T cells, resulting in enhanced tumor metastasis in various organs of the B16-F10 mouse model." (PMID 34576042, 2021). "Although calcitriol may induce VEGF expression in some cases, its overall anti-tumor effect may stem from the balance of pro-angiogenic and anti-angiogenic factors (such as simultaneous regulation of VEGF and Thrombospondin-1), rather than simply inhibiting angiogenesis." (PMID 40705722, 2025). "Therefore, it is also possible that the high expression of Thbs1 in CAF‐activated BMDMΦ might participate in the inhibition of the cytostatic and phagocytic activity of these cells on tumoral cells but not in the phagocytosis of beads." (PMID 37199012, 2023). "Thrombospondin-1 (TSP-1), a potent inhibitor of angiogenesis that predominantly acts through its receptor CD36, has been reported to inhibit inflammatory lymphangiogenesis, whereas TSP-1 did not inhibit tumor-induced lymphangiogenesis in a chemical skin carcinogenesis model." (PMID 33731707, 2021).
cancer (294 papers, 1995 to 2026). A tumor composed of atypical neoplastic, often pleomorphic cells that invade other tissues. "THBS1 expression reportedly increases in many cancer types and is often associated with poor prognosis." (PMID 41294700, 2025). "By reducing MMP-9 secretion, VD was also found to restore the epithelial state of cancer associated mesothelial cells (CAMs) by normalizing thrombospondin-1 (THBS1), thereby reducing ECM remodeling." (PMID 41374952, 2025). "Disruption of interactions between CD47 and THBS1 heightens cancer cell susceptibility to immune attack." (PMID 41019041, 2025). "EGFR and Wnt/β-catenin signaling are two of the pathways implicated in the oncogenesis and cancer progression induced by both THBS1 and THBS2, as well as in the activation of the EMT program." (PMID 38339060, 2024). "Combined with the previous studies, our results uncovered the prognostic, diagnostic, and therapeutic values of THBS1 in human cancers." (PMID 34804159, 2021). "Deletion of THBS1 is a rare event in most human cancers, and the observed loss of expression largely results from epigenetic effects of the altered oncogenes and tumor suppressor genes." (PMID 33925464, 2021). "Specifically in GC, decreased THBS1 expression has been associated with a poor prognosis, but higher expression in cancer tissue has been correlated with cell invasion and migration." (PMID 32117120, 2020). "Our data confirm plasma SAA1, PIGR, SPP24, FASN, and possibly THBS1 as potential biomarkers that are common to different types of malignant tumours and associated with Abnormal Savda." (PMID 25652121, 2015). "This contrasts with earlier studies where low levels of THBS1 expression have been associated with increased recurrence rates and decreased overall survival rates in several human cancers." (PMID 25051363, 2014). "THBS1, an angiogenesis inhibitor, is negatively associated with cancer progression." (PMID 39678510, 2024). "Interestingly, THBS1 levels are lower in the serum of cancer patients underlining its anti-angiogenic role, a finding that applies also to PCa." (PMID 32421745, 2020). "Among them, Cspg5, Fbn1, Thbs1, Pdpn, Etv4, Unc5a, Ntn1, and Nat8l were associated with the OC prognosis; Cspg5, Fbn1, Pdpn, and Unc5a were correlated with patient age; Fbn1, Mycn, Nat8l, Unc5a, and Ntn1 were significantly correlated with individual cancer stage." (PMID 36829196, 2023). "Importantly, Thbs1 is associated with bad prognosis in several human cancers." (PMID 35543624, 2022). "In this study, we identify a 4-protein sEV biomarker panel (thrombospondin-1, nidogen-1, pentraxin-3, and versican) based on proteomic profiles obtained from an isogenic cancer cell line model." (PMID 41881025, 2026). "THBS1 in the monocytes can also facilitate cancer metastasis and positively correlates with the mesenchymal characteristics." (PMID 40469525, 2025). "THBS1 plays an active role in suppressing cancer development by preventing angiogenesis, and was in this study upregulated in MC." (PMID 40778374, 2025). "One study demonstrated the instructive role of ECM stiffness in regulating exosome secretion and its effects on BC cell motility and migration, and identifies exosomal thrombospondin 1 (THBS1) as the master regulator of cancer invasion." (PMID 40691627, 2025). "Thrombospondin-1 (THBS1) is an extracellular matrix glycoprotein that modulates immune responses, cell adhesion, and angiogenesis, significantly impacting T2D and cancer." (PMID 40127075, 2025). "We did observe more protein complexes appearing in the migratory cancer cells, and THBS1 functions as an important mediator with TβRI and ITGAV." (PMID 39304722, 2024). "M1 TAMs polarized by exosomal thrombospondin 1 (THBS1) from OSCC cells can promote the EMT process and induce cancer stem cells (CSCs) through the IL6/Stat3/THBS1 feedback loop." (PMID 39744628, 2024).
cancer (continued). "Select genes that were found to be associated with chemoresistance in other cancers included GDF15, THBS1, CDKN1A and CLU." (PMID 38673926, 2024). "THBS1 promotes cancer cell migration and stimulates matrix metalloproteinases (MMPs) through integrin signaling, facilitating OSCC invasion." (PMID 38778403, 2024). "The uniform dysregulation of FN1, F5, and THBS1 across all cancer stages highlights these genes as possible biomarkers and their potential utility in cancer diagnosis and prognosis." (PMID 39456895, 2024). "Investigations on THBS in HNSCC have demonstrated that THBS‐1 exhibits high expression levels in HNC cells and is associated with cancer invasiveness and angiogenesis." (PMID 38946720, 2024). "In this research field, we recently found that the matricellular proteins thrombospondin 1 (THBS1) and 2 (THBS2) are highly expressed and released in the extracellular fluid (ECF) of the iCCA TME from cancer-associated fibroblasts (CAFs)." (PMID 38339060, 2024). "These M1-like TAMs promote EMT and cancer stem cell formation through the IL-6/Jak/Stat3/THBS-1 axis." (PMID 39200273, 2024). "Among them, the expressions of Cdkn1a, Hmga2, Thbs1 and Cdkn2a in MicroRNAs that promote cell differentiation in cancer pathways increased, indicating that the differentiation of SSCs is dominant." (PMID 38397131, 2024). "Our findings revealed that cancer had lower expression of THBS1, THBS3, and THBS4 compared to normal tissue, whereas the expression of THBS2 was higher." (PMID 38827236, 2024). "In our study we observed that TGFβ treatment of PC3U cells resulted in increased secretion of THBS1 which promoted migration and invasion of cancer cells." (PMID 39304722, 2024). "Thrombospondin-1 (THBS1) was identified as a prospective regulator of ECM stiffness-dependent cancer invasion involving matrix metalloproteinase and focal adhesion kinase." (PMID 37893211, 2023). "Analysis of the CRC dataset from the cancer genome atlas (TCGA) demonstrated a positive correlation between THBS1 and mesenchyme-related genes (VIM and FN1) and pan-myeloid markers (CD14 and CD33)." (PMID 37749092, 2023). "The secretome analysis of cancer cells post NVA-IT treatment showed that many proteins like thrombospondin-1, fibronectin, and vitronectin involved in cancer progression, metastasis, and angiogenesis have been affected." (PMID 37900279, 2023). "It has been reported that exosomal THBS1 promotes stiffness-dependent cancer invasion by engaging matrix metalloproteinases and focal adhesion kinases." (PMID 37124494, 2023). "Thbs1 is expressed by Lgr5+ cancer stem cells in vivo and induces YAP activation in neighbouring epithelial cells." (PMID 35543624, 2022). "mCHT inhibits the expression of pro-angiogenic factors, such as VEGF, VEGFR2, bFGF, and SDF1, and induces the production of angiogenesis inhibitors, such as thrombospondin-1, in both stromal and cancer cells, platelet factor-4, and endostatin." (PMID 36012949, 2022). "Most downregulation of THBS1 in cancers is epigenetic, resulting from promoter hypermethylation, altered expression of regulatory non-coding RNAs, or altered levels of oncogenic transcription factors." (PMID 35811717, 2022). "SWATH-MS identified a positive correlation between MMRN1 and thrombospondin 1 expression, which is differentially regulated in cancers, in the blood plasma of five cancers (colorectal, pancreatic, lung, prostate, ovarian)." (PMID 35132992, 2022). "Here, we found that cancer cell-derived THBS1 can ‘corrupt’ WT epithelial cells in organoids, independently of stroma-derived effects, allowing us to address the specific role of THBS1 on epithelial cells." (PMID 35543624, 2022). "CD47 performs a vital function in cancer therapy by binding to different SIRPα, thrombospondin 1, and integrin." (PMID 35697717, 2022). "Typically, in malignant tumors, antiangiogenic and antitumor mechanisms are activated by increased expression of an endogenous antiangiogenic factor, thrombospondin 1 (THBS1)." (PMID 36142283, 2022).
cancer (continued). "For example, methylation-induced silencing gene expression of the angiogenesis inhibitor thrombospondin 1 (THBS-1) inhibits the secretion of TGFß, which was correlated with increased metastasis, invasion, and poor prognosis in several types of cancers." (PMID 34552922, 2021). "The identification of thrombospondin-1 as an angiogenesis inhibitor in 1990 prompted interest in its role in cancer biology and potential as a therapeutic target." (PMID 33925464, 2021). "This review highlights progress in understanding thrombospondin-1 functions in cancer and the challenges that remain in harnessing its therapeutic potential." (PMID 33925464, 2021). "Thrombospondin 1 is a multifaceted player in cancer proliferation, invasion, migration and apoptosis through different interaction networks that are not completely elucidated." (PMID 34440012, 2021). "Proclarix (Proteomedix) combines tPSA and fPSA with cancer-related glycoproteins thrombospondin-1 (THBS1) and cathepsin D (CTSD) as well as age to calculate a patient’s probability of having clinically significant PC on biopsy." (PMID 34948334, 2021). "Using the TCGA PanCancerAtlas for Mutual Exclusivity analysis of pan-cancer mutations, we uncovered cooccurrence relationships of THBS2, THBS4, and THBS5 with THBS1; THBS4, THBS3, and THBS5 with THBS2; and THBS3 and THBS4 with THBS5." (PMID 34804159, 2021). "TGFB1 was reported to induce the expression of THBS1, resulting in stimulating migration of cancer cells and driving the expression of MMP3 (matrix metalloprotease 3) via integrin signaling, conducive to OSCC intrusion." (PMID 35237609, 2021). "Prete and others demonstrated that in cancer cells with BRAF mutations, therapeutic escape from BRAFi/MEKi was facilitated by pericytes that secreted thrombospondin-1 (TSP-1) and TGF-β1, both of which led to a rebound of pERK1/2, pAKT and pSMAD3." (PMID 34917620, 2021). "We mainly found that THBS1, THBS2, and THBS3 are dysregulated in various cancers, and their expression level is associated with the prognosis of patients." (PMID 34804159, 2021). "Many related studies have consistently illustrated an anti-angiogenesis effect of THBS1 in human cancer, although emerging evidence points to a huge transverse." (PMID 33244454, 2020). "We noted that the expression of THBS1 was higher in cancer tissues than in adjacent normal tissues in Derrico gastric datasets from the Oncomine database, which indicated that the results of the GSE33651 microarray were in agreement with the previous studies." (PMID 32801999, 2020). "We originally discovered two cancer-related proteins thrombospondin-1 (THBS1) and cathepsin D (CTSD) using a mass-spectrometry-based proteomics approach." (PMID 32421745, 2020). "Cancer cells in bone marrow produced vascular endothelial growth factor (VEGF) but its angiogenic effects were canceled by thrombospondin 1, which was released by endothelial cells in niches, thereby resulting in decreased tumor formation." (PMID 33050237, 2020). "THBS1 (Thrombospondin 1) is a matrix glycoprotein with controversial role in cancer, with some reports showing an antioncogenic function, and others a pro-oncogenic role." (PMID 32117120, 2020). "This immunoassay-based ELISA test is performed on the same blood sample as the sPSA test, measuring the cancer-related glycoproteins thrombospondin-1 (THBS1) and cathepsin D (CTSD)." (PMID 33339117, 2020). "In these DEGs, several cancer‐associated genes such as HOXC10, THBS1, CDKN2B, PAX2 and H19 were significantly associated with AML biology." (PMID 31794134, 2020). "HRG released from platelets have been shown to promote angiogenesis in cancer by interfering with thrombospondin 1 and thrombospondin receptor CD36-mediated antiangiogenic signaling." (PMID 30944671, 2019). "THBS1 was first discovered in platelets but has now been shown to have an important role in cancer development." (PMID 30850588, 2019).
cancer (continued). "For instance, NE and CG were found to degrade thrombospondin 1 in the pre-metastatic tumor microenvironment to promote cancer progression." (PMID 31010242, 2019). "Numerous studies on several cancer types including GBM11 indicate that THBS1 can modulate immune responses as well as GBM vascularisation." (PMID 30850588, 2019). "The main known function of the matricellular protein THBS1 is its anti-angiogenic and anti-inflammatory effect in various models, mainly in cancers and cardiac diseases." (PMID 29238343, 2017). "Among these eleven putative genes, including genes such as MYD88, FGFR2 and THBS1, stimulative or suppressive effects on cancers have been shown by the experiments." (PMID 28384236, 2017). "In contrast, only a small number of studies reported that THBS1 was significantly up- or down-regulated in different types of cancer." (PMID 27513329, 2016). "To confirm that some of these expressions change, we selected several proteins for validation by immunoblotting including Serpinb5 (Pai3), Icam5, Thrombospondin-1 (Thbs1) whose roles are well established in cancer." (PMID 27167202, 2016). "Cancer dormancy is induced in metastasized cancer cells by extrinsic factors, such as bone morphologic protein, thrombospondin-1, and TGF-β2, which are derived from the tissues where the cancer cells metastasized." (PMID 26083776, 2015). "One report showed binding of SFRP1 to thrombospondin-1, thereby inhibiting cancer cell adhesion and migration." (PMID 25033833, 2014). "A role in cancer progression and cancer inhibition has been ascribed to the protein, and different effects of THBS1 depending on the phase of the progression have been suggested." (PMID 24528603, 2014). "The function of THBS1, its prognostic effect in various cancers, and its regulation are controversial." (PMID 24195060, 2013). "Specifically, women whose cancers had high compared to low THBS1 protein expression had worse progression-free (PFS) and overall survival (OS)." (PMID 24195060, 2013). "Thrombospondin-1 (TSP-1) plays a fundamental role in cancer progression by regulating cell stromal cross-talk in the tumor microenvironment." (PMID 24348463, 2013). "Of these, thrombospondin-1 was the first protein recognized as an endogenous inhibitor of angiogenesis and has since become a popular target for the treatment of various cancers." (PMID 20671917, 2010). "As αβ-heterodimers, the integrins serve as receptors for ECM components, some of which (laminin and thrombospondin 1 – THBS1) are also highly expressed in the carcinoma tumors." (PMID 18811984, 2008). "THBS1 is a matricellular protein that functions in cell–cell and cell–matrix adhesion and is down-regulated in a number of human cancers." (PMID 17500590, 2007). "A similar ambiguity of their role in cancer progression was indicated for THBS1 and IGFBP7." (PMID 39960760, 2025). "THBS1 is also involved in the progression of various human cancers." (PMID 41438033, 2025). "The exogenous addition of FGF7 and THBS1 protein enhanced the migration ability of cancer cells." (PMID 38778448, 2024). "Interestingly, we observed that THBS1 was specifically deposited in the matrix at the migratory front of the cell, where it seems to pave the way for cancer cells to migrate." (PMID 39304722, 2024). "Deletion of TβRI or THBS1 in cancer cells prevented their migration and invasion." (PMID 39304722, 2024). "Additionally, an increase in THBS1 expression is inversely related to the sensitivity towards anti-cancer drugs." (PMID 38761291, 2024). "In contrast, THBS1 was consistently downregulated across all cancer stages." (PMID 39456895, 2024). "This EV-mediated metastasis may be driven by thrombospondin-1 (THBS1) which overexpressed in stiff EVs was observed to regulate cancer cell motility." (PMID 38630893, 2024). "THBS1 was involved in alveolar macrophage, interacting with the a3b1 complex of cancer cells." (PMID 37760429, 2023).